CT45A2 (cancer/testis antigen family 45 member A2)
Synonyms: CT45-2; CT45.2
Tractability: PROTAC: ubiquitination databases record sites on it.
Gene: Protein-coding gene on chromosome X (135,811,668 to 135,820,012, reverse strand). Ensembl gene ENSG00000271449.
Subcellular location (Human Protein Atlas): Nucleoli; Nucleoplasm
Homologues: Orthologues: rat Ct45a9 (29% identical), mouse Ct45a (27% identical), Caenorhabditis elegans ints-6 (17% identical), Drosophila melanogaster IntS6 (16% identical). Paralogues in human: CT45A8 (100% identical), CT45A9 (100% identical), CT45A3 (98% identical), CT45A1 (98% identical), CT45A5 (98% identical), CT45A6 (98% identical), CT45A7 (98% identical), CT45A10 (95% identical), SAGE1 (35% identical), INTS6L (32% identical), INTS6 (26% identical).
Diseases named in the same sentence as CT45A2 in open-access papers:
CT45A2 is named in the same sentence as 7 diseases in open-access papers, as found by Europe PMC text mining. Sharing a sentence is not in itself a finding about the gene and the disease. The quoted sentences say what the papers report.
acute leukemia (1 paper, 2010). A clonal (malignant) hematopoietic disorder with an acute onset, affecting the bone marrow and the peripheral blood. "Cytogenetics, fluorescence in situ hybridization (FISH), molecular studies (RT-PCR and LDI-PCR), and bioinformatic sequence analysis were used to characterize the CT45A2 gene as novel MLL fusion partner in pediatric acute leukemia." (PMID 20920256, 2010). "In the present study, we have identified the CT45A2 gene as a novel fusion partner of MLL in a pediatric patient with de novo biphenotypic acute leukemia (BAL), as a result of a cryptic insertion of 11q23 material in Xq26 resulting in a spliced MLL fusion." (PMID 20920256, 2010). "We have identified CT45A2 as a novel spliced MLL fusion partner in a pediatric patient with de novo biphenotypic acute leukemia, as a result of a cryptic insertion of 11q23 in Xq26.3." (PMID 20920256, 2010). "Since CT45A2 is the first Cancer/Testis antigen family gene found fused with MLL in acute leukemia, future studies addressing its biologic relevance for leukemogenesis are warranted." (PMID 20920256, 2010).
leukemia (1 paper, 2010). A malignant (clonal) hematologic disorder, involving hematopoietic stem cells and characterized by the presence of primitive or atypical myeloid or lymphoid cells in the bone marrow and the blood. "The phenotypic consequences of CT45A2 expression in the leukemia cells of this patient are currently unknown." (PMID 20920256, 2010).
cancer (2 papers, 2010 to 2017). A tumor composed of atypical neoplastic, often pleomorphic cells that invade other tissues. "We have identified a novel fusion partner of MLL, the CT45A2 gene, which is a member of the Cancer/Testis (CT) gene family cluster localized at Xq26.3." (PMID 20920256, 2010).
CT45A2 also shares sentences with these, for which no sentence is quoted: lung carcinoma (1 paper); paraganglioma (1); pheochromocytoma (1); tumour (1).